TPO (thyroid peroxidase)
Diseases named in the same sentence as TPO in open-access papers (continued):
Sharing a sentence is not in itself a finding about the gene and the disease.
thyroid (continued). "Almost half of women with TPO autoantibodies develop postpartum thyroid dysfunction, which may present as hyper- or hypo-thyroidism." (PMID 34946265, 2021). "Thyroid health problems may be indicated by increased levels of thyroid-related antibodies, including thyroglobulin antibodies (TgAb) and anti-thyroid peroxidase (anti-TPO)." (PMID 31979063, 2020). "Consideration of the relation of TPO antibody to thyroiditis and thyroid dysfunction could be one of the limitations of our study." (PMID 31443521, 2019). "The thyroid antigens most frequently used to diagnose and follow the AITDs are Tg, TPO, and TSH-R." (PMID 31906000, 2019). "Aim of this study is to find the frequency of various thyroiditis, study the cytomorphological features and correlate with clinical findings including radiological findings, thyroid function test, and anti-thyroid peroxidase antibodies (Anti-TPO antibodies)." (PMID 29686830, 2018). "This study has been undertaken to find out the frequency of various thyroiditis and study the cytomorphological features and correlate with clinical findings including radiological features, thyroid function test, and anti-thyroid peroxidase antibodies (Anti-TPO antibodies)." (PMID 29686830, 2018). "Also, the prevalence of anti-ENA was comparatively higher than the prevalence of ANA in thyroid positive, anti-TPO positive, and anti-Tg positive subjects." (PMID 30911555, 2018). "GD treatment is more complex and consists of reversible medical treatment for 12–18 months with thionamides, anti-thyroid drugs (ATDs) interfering with the TPO enzyme and thus thyroid hormone synthesis, or irreversible non-surgical (radioactive iodine) or surgical (thyroidectomy) treatment." (PMID 29372482, 2018). "Moreover, as its role with the expression of TG and TPO suggests, mutations at the FOXE1 locus in 9q22 have been associated with thyroid disorders such as congenital HT due to thyroid dysgenesis, primary HT, goiters, nonmedullary thyroid cancer, PTC, and TC." (PMID 28928994, 2017). "As already mentioned, patients with persistent autoantibody positivity, especially anti-TPO, may develop thyroid disease in the future." (PMID 29267515, 2017). "Therefore, anti-TPO represents an autoantibody with tissue-specificity and clinical significance unspecific to thyroiditis." (PMID 28349935, 2017). "The most common defect in thyroid dyshormonogenesis resides in TPO gene." (PMID 26761947, 2016). "In addition, there was a higher conversion rate from TPO-Abs negativity to positivity, showing a familial proneness for thyroid autoimmune reactivity." (PMID 27092550, 2016). "Furthermore, early markers of thyroid autoimmune involvement, such as anti-thyroid peroxidase antibodies (anti-TPO) or thyroid echographic alterations with euthyroidism, have more frequently been observed in CD patients compared with the healthy population." (PMID 28943613, 2015). "Moreover the titer of thyroid peroxidase antibodies is a predictor of the severity of postpartum thyroiditis and possible of recurrent disease." (PMID 24987536, 2014). "Sixteen percent of the women who are euthyroid and positive for TPO or TG antibodies in the first trimester will develop a TSH that exceeds 4.0 mIU/L by the third trimester, and 33%–50% of women who are positive for TPO or TG antibody in the first trimester will develop postpartum thyroiditis." (PMID 23762776, 2013). "More frequent assessment of thyroid function status and size during the course of therapy is recommended among middle aged females (≥50 years), patients with a family history of thyroid disease and those positive for thyroid auto-antibodies (anti-thyroid peroxidase and TSH receptor antibodies)." (PMID 23391071, 2013). "Among the thyroid tests, median TSH and median TPO Ab were significantly higher in the cases (consistent with Hashimoto’s Thyroiditis) who also had a significantly lower mean FT3 and iodine than the controls (p values 0.03, 0.001, 0.009 and < 0.001, respectively)." (PMID 23962199, 2013).
thyroid (continued). "Therefore, we consider first the development of antibodies to the immunogens, namely the TSHR A-subunit and in some cases Tg, before considering development of antibodies to TPO, thyroiditis and serum T4." (PMID 22970131, 2012). "Indeed, autoantibodies to thyroid self-antigens dramatically enhanced uptake of thyroid peroxidase (TPO) by APCs and subsequent activation of TPO-reactive T cells and blockade of FcγR markedly reduced this response." (PMID 23807906, 2012). "“Silent” thyroiditis is autoimmune and characterised by positive anti-TPO antibodies." (PMID 16363909, 2005). "High concentrations of anti-TPO antibodies are present in silent and post-partum thyroiditis." (PMID 16363909, 2005). "The clinical parameters of thyroid function can be used to predict the risk of developing OHSS, such as thyroid-stimulating hormone (TSH), free thyroxine (FT4), and thyroid peroxidase antibodies (TPO-Ab), enabling targeted preventive measures by healthcare professionals." (PMID 38725001, 2024). "The application of indicators including TSH, free T3, free T4, T3, T4, TG antibodies, TPO antibodies, and TR antibodies in human medical tests as a standardized procedure has proved the reliability of these sensitive indicators for diagnosis of human thyroid disease/thyroid dysfunction disease." (PMID 39195672, 2024). "However, some studies suggest that the presence of thyroid auto-antibodies, such as anti-thyroglobulin and anti-thyroid peroxidase, prior to starting ICI therapy may be associated with higher risk of developing thyroid-related irEEs." (PMID 37251665, 2023). "The presence of thyroid anti-TPO antibodies was found positive in 40% of hypothyroid pregnant females in an Indian epidemiological study, while an Iranian study reported 12.8 and 8.5% prevalence of anti-TPO and anti-TG antibody positivity in their population of 600 pregnant females." (PMID 33588796, 2021). "However, other findings such as the association between TPO and thyroid disease were not identified using this alternative method." (PMID 31924771, 2020). "We assume that the generally low expression in NSCs in cluster A reflects an immune suppressive state preventing autoimmunity, while a rise of these pro-inflammatory compounds precedes a conversion to TPO-Ab positivity and thus may reflect a very early stage of thyroid auto reactivity." (PMID 27092550, 2016). "Although measurement of thyroid antibodies does not give any indication of thyroid function, the presence of TPO antibodies may be associated with decreased thyroid functional reserve during pregnancy." (PMID 24624307, 2014). "The prevalence of ANA, P-ANCA, ASCA IgG, and anti-GAD and anti-TPO antibodies were slightly increased compared to healthy controls, but not at all to the same magnitude as in patients with Crohńs disease, ulcerative colitis, diabetes mellitus or thyroid disorders." (PMID 23776613, 2013). "Some reports suggest a potential correlation between TPO-Ab and ICB therapy-induced thyroiditis, yet findings remain inconsistent." (PMID 40575257, 2025). "HT is diagnosed by the presence of positive specific Thyroid Antibody Titers (TAT), Anti-thyroid Peroxidase (TPO), anti-thyroglobulin (Tg), as well as thyroid ultrasound, a complementary method that can be used in the evaluation of thyroid disorders." (PMID 41228508, 2025). "Thyroid abnormality was assessed through the current history of thyroid disease and laboratory tests - thyrotropin (TSH), free thyroxine (FT4), antithyroid peroxidase (anti-TPO) and antithyroglobulin (anti-TG) antibodies." (PMID 37598033, 2024). "Diagnosing ICI-related thyroid disorders requires vigilance and regular thyroid function screening, utilizing measurements of TSH, fT4, and TRAb, TPO-antibodies and TSH receptor antibodies, according to specific guidelines." (PMID 38345684, 2024).
thyroid (continued). "Thyroid peroxidase (TPO) is a key enzyme in the production of thyroid hormones and a major thyroid autoantigen in addition to thyroglobulin and the thyroid-stimulating hormone receptor." (PMID 36537574, 2023). "Recent guidelines recommend the measurement of serum autoantibody, IgG to thyroid peroxidase (TPO), which is related to not only thyroid diseases but also autoimmune diseases, to evaluate autoimmunity in patients with CSU." (PMID 35984815, 2022). "They found a significant higher frequency of TPO- and Tg-specific CD8+ T cells in PTC-thyroiditis patients compared with healthy controls." (PMID 36077831, 2022). "Possible mechanisms for post-vaccination myocarditis and thyroiditis are molecular mimicry between SARS CoV-2 spike protein and self-antigens (myocyte protein and thyroid peroxidase) as well as triggering of preexisting dysregulated immune pathways." (PMID 35581666, 2022). "The 11 selected thyroid-specific RNA transcripts (TPO, TG, GFRA2, IYD, PDE8B, WDR86, C16orf89, DGKI, DIO2, TSHR, and PAX8) were amplified from healthy volunteers and thyroid patients." (PMID 34512731, 2021). "There were statistically significant increases of anti-TPO, TSH, hemoglobin, and platelet in autoimmune group compared to the infective thyroiditis group (P < 0.05)." (PMID 33132691, 2020). "Multiple trials done in PCOS patients have shown a higher presence of thyroid-related antibodies such as anti-TSH, anti-TPO, and anti-Tg levels." (PMID 33391917, 2020). "All participants had thyroid evaluation in the form of measurement of thyroid-stimulating hormone (TSH), free thyroxine (FT4), antithyroid peroxidase antibody (TPO Ab), and antithyroglobulin antibody (Tg Ab)." (PMID 31157131, 2019). "Nineteen (27.5%) of 69 patients had abnormal thyroid autoantibodies including TGA, TPO-Ab, and TSH-RA; 10 of 21 seropositive MG patients were tested for thyroid autoantibodies, and 60% of these patients had thyroid autoantibodies." (PMID 25478208, 2014). "Ten to 20% of pregnant women are positive for thyroid peroxidase (TPO) or thyroglobulin antibodies and euthyroid, of whom 16% will develop high TSH values during pregnancy and 35–50% will develop postpartum thyroiditis." (PMID 23738229, 2013). "These RIs should be based on pregnant women with no known thyroid disease, optimal iodine intake, and negative anti-thyroperoxidase antibody (anti-TPO) status." (PMID 41399656, 2026). "Although thyroid autoantibodies (anti-thyroid peroxidase, anti-thyroglobulin) were not assessed due to cost limitations, the clinical profile was consistent with postpartum thyroiditis." (PMID 41496136, 2026). "Although frequently present in thyroid disorders, anti-TPO antibodies do not appear to directly influence treatment sensitivity." (PMID 41523860, 2025). "Our patient also exhibited thyroiditis, which aligns with evidence that Borrelia spirochetal proteins share antigenic properties with thyroid-related proteins such as the TSH receptor, thyroglobulin, and thyroid peroxidase." (PMID 40161058, 2025). "The case group had a higher likelihood of a history of autoimmune disease and thyroid disease, as well as a significantly higher percentage of individuals testing positive for ANA and anti-TPO antibodies (13 and 37%, respectively) compared to the control group (5% for ANA and 23% for anti-TPO)." (PMID 40740211, 2025). "A large-scale European study reported elevated TPO-Ab levels in 13.9% of women and 2.8% of men without thyroid disease." (PMID 40927297, 2025). "Thyroid-specific tumor and autoimmunity markers (calcitonin, thyroglobulin, anti-thyroglobulin antibodies, and thyroid peroxidase antibodies) were not included in the comparative analyses due to their non-uniform availability across the retrospective cohort." (PMID 41595547, 2025). "Thyroiditis and accompanying anti-TPO autoantibody positivity are conditions that should not be ignored by thyroidologists and thyroid-health providers." (PMID 39230146, 2024).
thyroid (continued). "One patient who discontinued treatment because of silent thyroiditis related to ropeginterferon alfa-2b had no history of thyroid dysfunction and was positive for anti-thyroid peroxidase antibodies and negative for anti-thyroglobulin antibodies at baseline." (PMID 38951434, 2024). "Although one patient had high TPO antibodies, the thyroid function tests were not clinically and ultrasonographically consistent with thyroiditis." (PMID 39024360, 2024). "This was a cross-sectional study including women with confirmed spontaneous subclinical hypothyroidism and an age- and body mass index (BMI)-matched control group without thyroid disease or circulating antithyroperoxidase (anti-TPO) antibodies." (PMID 39420912, 2024). "The correlation between mild to moderate PPD and TPO antibodies has been consistently observed in women, regardless of the incidence of postpartum thyroiditis." (PMID 37868409, 2023). "Metformin induced a significant reduction in anti-TPO Ab and anti-TG Ab levels in patients with HT and SCH, reduced TSH levels, and increased FT4 and FT3 levels in euthyroid patients with uninodular thyroid disease and insulin resistance." (PMID 37635968, 2023). "Somewhat surprising, two thirds of those with CC that had positive TPO neither declared thyroid disease nor levothyroxine consumption." (PMID 35668375, 2022). "The present analyses included 3859 individuals, without a previous thyroid disease diagnosis, and with negative thyroid peroxidase antibodies (TPO Abs) and thyroid-stimulating hormone (TSH) levels of 0.1-20 mIU/L." (PMID 35978396, 2022). "Our findings indicate that thyroid abnormalities may be more frequent at follow-up (anti-TPO 19%, TSH abnormalities 15% and low T4 11%) than at baseline (anti-TPO 11%, TSH abnormalities 10% and low T4 0%)." (PMID 33559023, 2022). "In conclusion, to date, the role of the TPO Ab status in patients with Graves’ hyperthyroidism has not been well studied as a predictive parameter for thyroid functional outcome after first administration of RAI." (PMID 35687484, 2022). "In a study by Groer and Vaughan, anti-TPO positive women had significantly higher scores for depression, anger, and total scores of mood disturbance postpartum than anti-TPO negative women, regardless of the development of postpartum thyroiditis (n = 25)." (PMID 35351167, 2022). "On the other hand, a significant number of patients had anti-TPO or anti-TG antibodies despite no thyroid disease recorded." (PMID 35109858, 2022). "Reference range determinations should only include otherwise healthy reference subjects that are thyroid peroxidase antibodies-negative and free of pre-existing thyroid disease, with an optimal iodine intake." (PMID 35324464, 2022). "In the second sub-study, thyroid hormones (T3, T4, TSH) and thyroid auto-antibodies levels (anti-TG, anti-TPO) of 72 healthy subjects with no history of thyroid disease were examined before (D1) and one month after completion of the second dose (D50)." (PMID 35273575, 2022). "This is probably explained by the fact that at the initial workup of a patient with thyrotoxicosis, a positive TPO Ab status with absent TSH-R Ab or low uptake at scintigraphy directs the diagnosis towards silent thyroiditis." (PMID 35687484, 2022). "Out of the nine TPO positive patients, six did neither declare thyroid disease nor levothyroxine treatment." (PMID 35668375, 2022). "To date, the role of the TPO Ab status in patients with hyperthyroidism due to Graves’ disease prior to RAI administration has not been well studied as a predictive factor for thyroid functional outcome." (PMID 35687484, 2022). "After excluding thyroid peroxidase antibody (TPO-Ab) positive and/or thyroglobulin antibody (TG-Ab) positive women, previous thyroid disease, a lack of iodine intake, reference values were calculated by 2.5th to 97.5th percentiles." (PMID 33305315, 2021).
thyroid (continued). "Reference range determinations should only include pregnant women with no known thyroid disease, optimal iodine intake, and negative TPO-Ab status’." (PMID 33305315, 2021). "Second, multiple thyroid indicators were measured, and the large sample size enabled us to divide the population into different groups according to the TSH or clinical thyroid status in combination with the TPO Ab status." (PMID 33613448, 2020). "Patients with thyroiditis as expected had significantly higher values of thyroid autoantibody, anti-TPO, and anti-TG, as well as TSH, compared to MS without thyroiditis." (PMID 33132691, 2020). "In addition, the development of autoantibodies against thyroid proteins mainly thyroid peroxidase (TPO), thyroglobulin (Tg), and thyroid stimulating hormone (TSH) receptor can lead to thyroid disorders." (PMID 31320934, 2019). "Both TPO-abs and Tg-abs were significantly related to RCBD, even after controlling for gender, age, marriage status, education, antidepressants treatment, comorbidity of thyroid diseases, and thyroid function (serum levels of FT3, FT4 and TSH)." (PMID 31791284, 2019). "Among PV patients that did not report a history of thyroid disease (n = 177), 12.99% (n = 23) were found to still carry autoantibodies directed against either/or anti-TPO and anti-Tg, albeit with considerably lower levels of anti-Tg (3.95%, n = 7)." (PMID 29675021, 2018). "AITDs which corresponded to 15.3% (18/72; excluding patient number 3 due to negative thyroid autoantibodies) of patients showed positivity to either anti-TPO or anti-Tg." (PMID 30515422, 2018). "The majority of reports indicate that TPO is in low form or lack of expression in thyroid malignant tumor, and TPO immunostaining has higher sensitivity and specificity to distinguish thyroid benign and malignant disease." (PMID 30005075, 2018). "In clinical trials, half the patients who tested positive for TPO Ab at baseline and a quarter of patients who tested negative developed a thyroid event." (PMID 29372482, 2018). "A total of 14825 subjects with thyroid-related symptoms were tested at Vibrant America Clinical Laboratory for thyroid markers (TSH, FT4, anti-TPO, and anti-Tg) and an autoimmune panel (ANA panel and ENA-11 profile) from March 2016 to May 2018." (PMID 30911555, 2018). "The concentration of anti-TPO autoantibodies in CSF was very low compared to plasma in both subjects with thyroid and without thyroid disease (P = 0.007)." (PMID 26798549, 2015). "The presence of a thyroiditis was suggested by the positivity of anti-TPO antibodies, which were absent at baseline, and the suppressed thyroid radioiodine uptake." (PMID 25045352, 2014). "Our patient had negative thyroid peroxidase antibodies, positive thyroglobulin antibodies, and past history of thyroid disease." (PMID 24987536, 2014). "There were 4 TPO negative women who developed symptoms and signs of thyroid disease, including out of range TSH levels." (PMID 25405057, 2014). "The TPO positive women who did not develop thyroiditis were different in hypo- and hyperthyroid subscale scores compared to TPO negative women." (PMID 25405057, 2014). "For instance, a recent Italian study showed that 37.2% of thyroid peroxidase (TPO) antibody-positive women had postpartum thyroiditis, versus 1.7% of the TPO antibody-negative women." (PMID 22577597, 2012). "Autoantibodies to thyroid peroxidase (TPO) and thyroglobulin (Tg) are reflections of thyroid disease rather than causative agents." (PMID 22530160, 2012). "Anti-TPO was not available, which can also be helpful in the diagnosis of thyroid disease as an autoimmune disease." (PMID 22339761, 2012). "Antibodies to Tg and TPO were only observed at euthanasia, not at the earlier time point, in Lo-expressor transgenics that developed thyroiditis." (PMID 22970131, 2012).